CD47 (CD47 molecule)
Diseases named in the same sentence as CD47 in open-access papers (continued):
Sharing a sentence is not in itself a finding about the gene and the disease.
cancer (continued). "Besides the cGAS/STING pathway, other immunomodulatory mechanisms involved in cancer include Toll-like receptor (TLRs), RIG-I, NLRP3, and CD47-SIRPα pathways." (PMID 39318624, 2024). "For instance, blocking the CD47-SIRPα axis—the “do not eat me” signal—can enhance the phagocytic ability of CAR-Ms against cancer cells." (PMID 39421021, 2024). "Unfortunately, further development of this agent and other CD47 inhibitors is being halted due to lack of clinical benefit seen across several other cancer types." (PMID 38473300, 2024). "Binding to CD47 triggers inhibitory signaling through SIRPα that prevents macrophage phagocytosis of nonmalignant and cancer cells." (PMID 38495618, 2024). "Combining with CD24 to deliver the “do not eat me” signal, CD47, an immune checkpoint receptor that is frequently dysregulated in malignant tumors, inhibits macrophage-mediated phagocytosis." (PMID 39256364, 2024). "Notably, some immune checkpoints such as CD47/SIRPα and CD24/Siglec10 successfully hamper macrophage phagocytosis, thus disrupting the removal of cancer cells via macrophages." (PMID 39409876, 2024). "Reculstering of IFNγ pathway genes showed a shifted expression profile in the IFNγ pathway in sh61A CAL 27 cells, with pronounced downregulation of CD274 and CD47, reinforcing the conclusion that TRMT61A is critical to the reactive upregulation of PD-L1 on cancer cells during inflammation." (PMID 38730256, 2024). "This suggests that mechanisms mediating IFT57 coregulation with CD47 are intrinsic to cancer cells, but this does not exclude additional contributions from IFT57 co-expression with CD47 mRNA in nonmalignant cells in stroma of the tumors analyzed in TCGA." (PMID 39201643, 2024). "In coculture assays, only osimertinib rendered the cancer cells more vulnerable to the anti-CD47 antibody, whereas neither erlotinib or gefitinib inhibited cell growth as single agents nor in concert with CD47 blockade." (PMID 38483480, 2024). "Our results therefore provide nuance to previous research highlighting the negative impact of CD47 in various cancers, including OC." (PMID 39138571, 2024). "CD47, also known as “do not eat me” signal, prevents the phagocytosis of cancer cells by interacting with signal regulatory protein alpha (SIRPα) on macrophages or other myeloid cells, preventing the cytoskeletal rearrangement needed for phagocytosis." (PMID 38414061, 2024). "Recent studies revealed CD47’s co-expression with IFT57 and its impact on cancer prognosis, suggesting dual targeting of CD47 and IFT57 may enhance efficacy and reduce CD47-targeted therapy’s side effects." (PMID 39652550, 2024). "The presence of CD47 on cell surfaces sends an inhibitory signal to macrophages, effectively signaling “do not eat”, which allows cancer cells to dodge immune elimination." (PMID 39457618, 2024). "Coexpression of CD47 and IFT57 mRNAs and correlations with overall survival in human cancers." (PMID 39201643, 2024). "Compared to other cancer types, SKCM ranks within the middle range of CD47 expression." (PMID 38414061, 2024). "In addition, since the cancer cell cluster C6 was characterized by concurrent enrichment of liver CSCs markers CD24, CD47 and ICAM1, we further sought to confirm the interaction between cluster C6 cancer cells and M2-like TAMs using TCGA-LIHC cohort." (PMID 38169544, 2024). "Taken together, Tug1 enhances the recruitment of Ybx1 to the promoter regions of Pdl1 and Cd47 to promote their expression, and then inhibits the function of CD8+ T cell and the phagocytosis function of macrophages toward cancer cells, thereby regulating the antitumor immune response." (PMID 38981064, 2024). "Immunological investigations unveiled a robust correlation between CD47 expression and T-cell infiltration rather than T-cell exclusion across multiple cancer types." (PMID 38720108, 2024).
cancer (continued). "Notably, when considering mechanisms to counteract cancer’s immune evasion tactics, CD73 emerged as more prevalent and bore a greater prognostic significance than PD-L1 and CD47 in HCC." (PMID 38914802, 2024). "The interpretation of positive or negative correlations between CD47 expression and cancer survival should also be reevaluated." (PMID 39201643, 2024). "Blocking CD47 with anti-CD47 antibodies disrupts this inhibitory interaction, allowing the pro-phagocytic signal from CALR to dominate and facilitate the destruction of cancer cells." (PMID 39682299, 2024). "Therefore, further Pearson analysis was conducted to investigate the correlation between GPR65 and common cancer immune checkpoint inhibitors, such as CD200R1, CD47, HAVCR2, TIGIT, CTLA4, LAG3, and PD1." (PMID 38218960, 2024). "Interestingly, we found CD47 partially colocalized with LAMP1, a lysosome marker, in all of HBE normal epithelial cells and A549, H1299 cancer cells." (PMID 36823443, 2023). "CD47 is IFN-γ-stimulated genes (ISGs) and prevents the phagocytosis of macrophages, leading to the cancer immune escape, and this effect could be inhibited by Abrine both in vivo and in vitro." (PMID 37334368, 2023). "Another CD47 targeting bsAB, IBI322, with a dual specificity for CD47 and PD-L1, is also being tested in several clinical trials in patients with advanced malignant tumors (NCT04328831, NCT04912466, NCT04338659) and hematologic malignancies (NCT04795128), but no clinical data has been reported yet." (PMID 36900399, 2023). "CD47 is a signaling molecule known as a “do not eat me” signal, which is overexpressed by cancer cells." (PMID 37510328, 2023). "Furthermore, inhibitory antibodies against CD47 or SIRP-α increase phagocytosis by macrophages and suppress cancer progression." (PMID 36768216, 2023). "Moreover, the percentage of CD47 colocalized with LAMP1 decreased in A549, H1299 cancer cells compared to that in HBE normal cells." (PMID 36823443, 2023). "The four murine cancer cells were infected with MyxV_0100 and expression of the cytokines IFN-γ, GM-CSF, IL-6, IFN-β, and the immune checkpoint-related genes FLT3L, OX40L, PD-L1, and CD47 were found elevated." (PMID 37835397, 2023). "Differences in the ERM proteins responsible for the cellular membrane localization of CD47 may be, at least in part, due to the divergent expression profiles of ERM depending on cancer cell type." (PMID 37189735, 2023). "In addition to playing critical roles in cancer and the TME, CD47 also functions in many other diseases." (PMID 36882399, 2023). "As observed with CD47, expression of CD169 correlates with a dismal prognosis in cancer patients." (PMID 38033495, 2023). "It is also reasonable to speculate that the combination of KRAS inhibitors and immune checkpoint inhibitors, including inhibitors of PD-1/PD-L1 or CD47/SIRPα, could provide synergistic benefits to patients with KRAS-driven cancers." (PMID 36413402, 2023). "CD47, a cell surface protein expressed on multiple cell types, including cancer cells, acts as a key regulator of the TME and represents a potential target for cancer therapy." (PMID 38188674, 2023). "The CD47 expressions in a library of cancer cell lines were quantified by Quantum MESF (Molecules of Equivalent Soluble Fluorochrome) microspheres, demonstrating the high CD47 expression (344056 ± 21945 CD47 molecules per cell) of the 4T1 cells." (PMID 36683161, 2023). "Some cancers, like blood cancers, tend to be highly sensitive to CD47 signaling blocking therapies but not to CD24 signaling inhibitors, while others, such as ovarian cancer, are more responsive to CD24 signaling blocking therapies." (PMID 37484024, 2023). "The present analysis found elevated expression of CD47 not only positively correlated with PD1, PD-L1, CTLA4, but also with multiple other immune checkpoints such as IDO1, CD40, CD160, CD86, CD44 across various cancer types." (PMID 35697717, 2022).
cancer (continued). "Moreover, CEP192 was also discovered to be positively correlated with cancer stem cell markers including CD24, SOX9, CD47, and POU5F1 (OCT4)." (PMID 36238304, 2022). "In human or murine triple-negative breast cancer cells treated with carboplatin, doxorubicin, gemcitabine, or paclitaxel, expression of CD47, CD73, and PDL1 changed in a HIF-dependent manner and consequently, increase in the ability of cancer cells to evade innate and adaptive immunity was observed." (PMID 36139678, 2022). "Six of the cancer types show a significantly increased hazard ratio, whereas three of them significantly decreased hazard ratios with higher CD47, and others show no significance." (PMID 35697717, 2022). "Membrane proteins from red blood cells contain high CD47 levels and can inhibit phagocytosis, while membrane proteins from MCF-7 cancer cells contain specific adhesion proteins that can adhere to homologous cancer cells." (PMID 36727049, 2022). "In addition, Il18, Tnf, Ptgs2, Cd47, Cxcl1, and Csf1 were more highly expressed in STOSE tumors, including in the cancer cells, supporting the influence of TAMs in these tumors." (PMID 36311166, 2022). "Prior to this study, no clinical studies evaluated CD47 blocker combined with CAR-T cell therapy in cancers." (PMID 35978372, 2022). "As some preclinical studies and clinical data have demonstrated the promise of targeting phagocytosis checkpoints, macrophage phagocytosis checkpoints, including CD47, CD24, stanniocalcin 1 (STC1), are potential targets for cancer immunotherapy in patients with advanced cancers." (PMID 35152264, 2022). "Patients with positive CD47 expression had a poorer prognosis for cancer-specific survival (CSS) than patients with negative CD47 expression (p = 0.003)." (PMID 36291980, 2022). "The expressions of CD47 and TMB were significantly different among various cancer types." (PMID 35697717, 2022). "Using syngeneic mouse models of cancer, rather than transplanted xenografts, they first demonstrated that the therapeutic effect mediated by the CD47 blockade is specifically CD8+ cytotoxic T cell–dependent." (PMID 36081498, 2022). "Once this first line of immune surveillance is evaded, the cancer cell population will no longer benefit from CD47 up-regulation, but will rather need to escape T-cell-mediated eradication." (PMID 36611344, 2022). "Overexpression of YAP rescued the defect in the expression of IL-1β and GM-CSF cytokines and CD47 expression in SIRPγ-knockdown cancer cells, supporting the notion that SIRPγ acts through the Hippo/YAP pathway to regulate the expression of IL-1β, GM-CSF, and CD47." (PMID 35229723, 2022). "Given the potential antigen-presenting advantages of CD47 blockade in improving adaptive immunity function when combined with CD8+ T cells, further research into the combination of CD47 blockade with CAR-T cells for cancer therapy is critical." (PMID 35978372, 2022). "Fifthly, some literatures revealed that CD47/TSP-1 pathway also has pleiotropic effects on immunity system and may present a new target for potential cancer therapeutics." (PMID 36081498, 2022). "In addition, HSPA5 was positively and significantly correlated with CD47 expression (p < 0.0001) and induced by CD47-overexpression in the OECM-1 and OC-2 OSCC cancer cell lines." (PMID 35678681, 2022). "Firstly, despite that IHC is a well-established and is a routinely used method for the determination of protein-level alterations in cancer specimens, there are no standardized protocols regarding CD47 and PD-L1 evaluation." (PMID 36399951, 2022). "But when tumorigenesis occurs in humans, as CD47 is expressed on the surface of cancer cells, macrophages not only fail to recognize and engulf it but promote it to complete metastasis in the super-early stage." (PMID 35123417, 2022). "The interaction between CD47 and SIRPα transmits an inhibitory ‘do not eat me’ signal resulting in cancer cell evasion of immune detection and clearance." (PMID 36465350, 2022).
cancer (continued). "It seems high expression of CD47 was negative with TMB/MSI in several poor prognosis cancers, while positively with TMB/MSI in a few favorable cancers." (PMID 35697717, 2022). "When investigating the key immunotherapy targets, the IPRP score and CD47 expression were significantly correlated in 15 cancer types (p < 0.05); only TCGT showed a negative correlation, while the other cancers had positive correlations." (PMID 35945345, 2022). "The interaction of macrophage signal-regulatory protein alpha (SIRP-α) with a glycoprotein CD47 direct signal for “do not eat me”, which helps cancer cells to grow during immune evasion." (PMID 35879772, 2022). "Among these, we found interactions that may constitute potential targets for CAFs-based therapies, such as THBS2/THBS3 (myCAF2) and CD47 (cancer cells) or between MDK (CAFs) and SDC2/SDC4/NCL (cancer cells)." (PMID 36352420, 2022). "Similar to MCL cell lines and regardless of the high expression of CD47, the specific increase in phagocytosis in carcinoma lines was significantly higher for CD24 than for CD47 antibody treatment for all CD24+ cells." (PMID 35625912, 2022). "CD47 mRNA expression is positively correlated with SLFN11 mRNA expression in a subset of human cancers but not in the corresponding nonmalignant tissues in TCGA." (PMID 33925464, 2021). "Anti-CD47/PD-L1 immunotherapies aiming to enhance antitumor immunity are being intensively investigated and show promising results in cancer therapy; however, not all patients treated with these new drugs respond." (PMID 33731702, 2021). "Dual-target small molecule inhibitor (SMI) co-targeting the CD47/SIRPα and TIGIT/PVR may also exert exciting effects in the cancer immunotherapy." (PMID 34068552, 2021). "The “do not eat me” signal CD47, overexpressed on the surface of cancer cells, forms a signaling complex with signal-regulatory protein α (SIRPα), a myeloid-specific immune checkpoint, enabling the escape from macrophage-mediated phagocytosis." (PMID 34683963, 2021). "Based on our knowledge, there seems to be no study to clearly show the relationship of CD47 expression on cancer cells with stromal CD163+ macrophages." (PMID 33765961, 2021). "Indeed, CD47 is upregulated in a number of cancer cells, notably by MYC oncogene, a transcription factor, which binds promotor of cd47 and Pdl-1 genes." (PMID 34925315, 2021). "To date, the interaction between cancer cell and immune cell proteins (e.g., CD47–SIRPα) under oxidative stress has not yet been investigated by computer simulations." (PMID 33540720, 2021). "CD47-blocking antibodies have shown efficacy in preclinical cancer models and early clinical trials, but these act primarily by blocking CD47 interactions with SIRPα rather than TSP1." (PMID 33925464, 2021). "Interestingly, CD47 is a conserved APA target in both LUAD data sets that we analyzed here, its 3′ UTR becoming shorter in cancer cells compared to lung alveolar cancer cells." (PMID 34521731, 2021). "CD47 (also known as MER6 or OA3) is a transmembrane protein expressed on normal and cancer cells." (PMID 34943817, 2021). "Such high CD47 expression was proposed to protect cancer stem cells from SIRPα-dependent macrophage clearance, but a cell-autonomous signaling function of CD47 in cancer stem cells was not considered." (PMID 33925464, 2021). "Furthermore, CD47 has been reported to regulate epithelial–mesenchymal transition (EMT) and cancer stemness." (PMID 33799989, 2021). "Supported by pre-clinical data demonstrating robust anti-cancer activity in AML and MDS by anti-CD47 antibody, clinical trials using Hu5F9-G4 (magrolimab), in combination with azacitidine demonstrated exciting results in both intermediate to very high risk MDS patients and in untreated AML patients." (PMID 33757574, 2021). "Cancer immunotherapy targeting CD47 has demonstrated success at the preclinical level and is now under clinical investigation for various human malignancies." (PMID 33917794, 2021).
cancer (continued). "Based on these observations, both monotherapy with CD47–SIRPA axis-targeting drugs and combination therapy with other anti-cancer antibodies may be applied to patients with CRC." (PMID 33799989, 2021). "CD47 and PD-L1 blockades are revolutionizing the treatment of various cancer types, but not all patients treated with these new drugs respond." (PMID 33731702, 2021). "Our study demonstrated that bi-SP with modified treatment indices may have a potential to treat CD47+ and EGFR+ cancers in the clinic." (PMID 34305918, 2021). "IMC-002 also showed selective binding to CD47 on cancer cells but not on RBCs, avoiding agglutination in vitro." (PMID 34584838, 2021). "Consequently, further research pertaining to the specific functions and roles of CD47 and SIRP is required prior to its exploitation as a potential target in the treatment of various neurodegenerative diseases and cancer." (PMID 34203368, 2021). "SLFN11 expression is also strongly correlated with the expression of CD47, a cell surface marker that sensitizes cancer cells to chemotherapy and radiotherapy, in RCC, while exogenous SLFN11 overexpression sensitizes CD47 negative cancer cells to radiotherapy." (PMID 34571887, 2021). "We found that CD9 was co-expressed with CD63-enriched UEVs, but not the CD47, which is over-expressed on EVs derived from cancer cells and involved in cancer metastasis." (PMID 34349163, 2021). "From these results, it is evident that Gal-9-mediated trogocytosis of cancer cells does not solely rely on the downregulation of CD47, but also stems from direct activation of neutrophils by Gal-9." (PMID 35052746, 2021). "Thanks to its unique mode of action, TAX2 does not recapitulate the hematologic toxicities related to CD47 blockade, hence reaching the full potential of targeting this axis for cancer therapy." (PMID 34638503, 2021). "By correlating drug sensitivity with the gene expression of cancer cell lines (n = 670), we identified Dasatinib, a potent Abl/Src inhibitor, with the efficacy negatively correlated with several immune biomarkers (CD274, CD47, PDCD1LG2), that are preferentially expressed by cancer cells." (PMID 32824422, 2020). "CD47 is expressed on the surface of non-malignant cells as well as multiple types of cancer cells and can bind to the SIRPα transmembrane protein on myeloid cells (especially macrophages) to form the CD47-SIRPα signaling complex." (PMID 32082311, 2020). "CD47 and HER2, two well-defined cell surface receptors with critical biological functions, were found overexpressed in an array of human cancers including 1085 BC compared to the counterpart normal tissue via analysis of TCGA databases using the web-tool GEPIA." (PMID 32929084, 2020). "Activation of CD47 in T cells mainly leads to the suppression of their immune response, while the interaction of CD47 with SIRPα or TSP-1 induces proliferation and activation of antigen-specific T cells, thereby improving the immune response to cancer cells." (PMID 32733941, 2020). "Indeed, compared to the wild-type cancer cells, the radioresistant counterparts (MBA-MD-231/C5 and MCF7/C6) demonstrated strikingly elevated protein levels of CD47 and HER2." (PMID 32929084, 2020). "IgA antibodies against receptors expressed by cancer cells (Her2, EGFR) could enhance neutrophil-mediated trogocytosis of cancer cells if the CD47-SIRPα innate immune cell checkpoint was simultaneously blocked." (PMID 32849639, 2020). "Widely regarded as a “don't eat me” signal, CD47 helps maintain immunotolerance by non-malignant cells under physiological conditions, but this same molecule can aid in the survival of cancer cells in various cancer types." (PMID 32082311, 2020). "CD47 is likely involved in the process of evading immunological eradication, and FOXP3 is mainly considered as a biomarker of Treg cells that impede the antitumor immune responses in cancer patients." (PMID 32118031, 2020).